PKD1 (polycystin 1, transient receptor potential channel interacting)
Diseases named in the same sentence as PKD1 in open-access papers (continued):
Sharing a sentence is not in itself a finding about the gene and the disease.
Renal cyst (continued). "As Lkb1 activity appears to be lost in Pkd1 mutants and as Lkb1 can suppress cystic growth in adult kidneys, we hypothesized that we may be able to target pathological growth in cystic kidneys in vivo by targeting glutamine metabolism." (PMID 29483507, 2018). "Similarly, the Pkd1nl/nl mice with 13%–20% of normal Pkd1 transcript display distal renal cysts and died at 1–2 months of age or even later." (PMID 26805887, 2016). "Because of parental history of bilateral renal cysts, PKD1 and PKD2, genetic testing was ordered." (PMID 26501044, 2015). "In addition, in humans, ADPKD is a heterozygous state, whereby mutations leading to loss of one PKD1 or PKD2 allele is combined with somatic mutations in the kidney (i.e., a second hit) to cause renal cystic disease." (PMID 23029375, 2012). "A high level of complexity in the molecular pathobiology was found in Pkd1-/- cystic kidneys." (PMID 21518438, 2011). "Pkd1-/- mutant embryos show numerous large renal cysts at E17.5." (PMID 21518438, 2011). "In addition, the epithelium of both ADPKD cystic kidneys and Pkd1 mutant kidneys displayed enhanced mTORC1 activity, as evidenced by immunohistochemical analysis of S6K and mTOR phosphorylation levels." (PMID 19863783, 2009). "Moreover, the number of renal cysts is different in PKD1 and PKD2 patients." (PMID 40362206, 2025). "In comparison, SKAT-O identified only PKD1 and PKD2 after p-value adjustment, whereas PERADIGM identified an additional candidate gene, IFT140 is a well-established gene in ciliopathies that has recently been implicated as a monogenic cause of renal cyst formation." (PMID 41411243, 2025). "Indeed, increased expression of ANO1 (3.7×) was observed in our PKD1 renal cysts." (PMID 39000280, 2024). "In addition to somatic mosaicism, PKD2 (n = 5) and PKD1 non-truncating (n = 3) mutations, which are typically associated with mild cystic kidney disease, were found in 8 of 9 (88.9%) mutation-positive patients with atypical imaging patterns in our study." (PMID 36807559, 2023). "Furthermore, considering the clinical similarity of ADPKD with other kidney cystic diseases, causing incorrect clinical diagnosis in the absence of familial history, molecular study for PKD1 with or without PKD2 in suspected patients is recommended." (PMID 32957937, 2020). "Therefore, we investigated whether trehalose treatment reduces renal cyst formation in a Pkd1-hypomorphic mouse model." (PMID 30585217, 2018). "Utilizing Pkd1 knockout mice and the SMYD2 inhibitor, AZ505, we showed that SMYD2 is a critical mediator of renal cyst growth in ADPKD." (PMID 35847973, 2022). "Disruption of PKD1 results in ADPKD type 1, characterized by a progressive onset of bilateral renal cysts, cysts present in other organs such as the liver, abdominal wall hernias, and vascular abnormalities." (PMID 30792735, 2019). "Increased levels of GSK3β phosphorylation, β‐catenin, and cMyc expression in all cystic kidney samples demonstrate that activation of the Wnt/β‐catenin signaling pathway is another common feature of human ADPKD and Pkd1 cKO mice." (PMID 27356569, 2016). "Increased nuclear localization of Id2 in renal epithelial cells has been reported in kidneys of PKD1 and PKD2 patients, and in Pkd1 knockout mice, which contributes to abnormal epithelial cell proliferation and differentiation in cystic kidneys." (PMID 26110849, 2015). "In the context of translational research, the observation of renal cysts in human patients with collagen IV gene variations, even without concurrent PKD1 or PKD2 variations, has opened new avenues for understanding the pathogenesis of renal cystic diseases." (PMID 40565535, 2025). "Currently, it is recommended that genetic studies be extended in patients with bilateral renal cysts who do not have variations in PKD1 or PKD2 to avoid misdiagnosis." (PMID 40565535, 2025).
Renal cyst (continued). "In this study, we found that gene expression profiles of human PKD1 renal cysts, regardless of their tubular origins, were consistent with the Warburg effect and had globally depressed mitochondrial oxidative metabolism." (PMID 39000280, 2024). "ADPKD was induced at 4 weeks of age and kidneys were collected at 12, 18 and 20 weeks of age, at which point advanced cystic kidney disease had developed in mice lacking Pkd1." (PMID 38191531, 2024). "Accumulating evidence suggests that therapeutic AMPK activation (e.g., metformin, 2-deoxyglucose or dietary interventions) attenuates cystic kidney disease severity by inhibiting mTORC1, CFTR, inflammation/fibrosis, and restoring mitochondrial energy metabolism in Pkd1 mutant animal models." (PMID 36743216, 2023). "Unlike human patients, who begin developing cysts during the fetal period, monoallelic PKD1 KO pigs do not display renal cysts neonatally." (PMID 34980882, 2022). "The protein products of PKD1 and PKD2 are transmembrane proteins called polycystin-1 (TRPP1, PC1) and polycystin-2 (TRPP2, PC2), respectively, whose localization to primary cilia was an essential clue in directly linking primary cilia to renal cysts." (PMID 36267587, 2022). "ASNS was found to be upregulated in cells lacking the Pkd1 gene, in cystic kidneys derived from Ksp-Cre:Pkd1flox/−, and in a subset of microarrays from humans and murine kidneys when compared to the corresponding controls." (PMID 34901057, 2021). "Cystic kidney disease is the second most frequent renal manifestation of TSC and can be triggered by the biallelic inactivation of TSC1/TSC2 alone or as the result of deletion events that also affect the PKD1 locus located adjacently in chromosome 1646." (PMID 34764250, 2021). "The TGFβ/Smad2 pathway is known to be hyperactivated in kidneys lacking Pkd1 and to induce kidney fibrosis, a prevalent feature of cystic kidneys." (PMID 32651191, 2020). "In tests of these hypotheses, both PKD1 and PKD2 transgenic rodent models exhibited renal cysts and other organ abnormalities." (PMID 31979107, 2020). "None of the unsolved patients had have family history of kidney disease, therefore mutations in autosomal recessive genes that lead to ARPKD-like phenotypes such as the DZIP1L or even in dominant cystic kidney disease genes such as HNF1B, PKD1 and PKD2 that often occur de novo are possible." (PMID 32799815, 2020). "The direct comparison of PKD1 and PKD2 patients as well as patients with other cystic renal diseases may allow the identification of genotype-specific markers that might be more closely linked to early disease-initiating processes." (PMID 23326375, 2013). "PKD1V/V mice have severely cystic kidneys at postnatal stages, but have no embryonic lethality in contrast to PKD1 knock-out mice." (PMID 20808796, 2010). "As expected Pkd1−/− fetuses had severe cystic kidney disease, edema and polyhydramnios due to the lack of fetal incorporation of tetraploid cells." (PMID 20862291, 2010). "Importantly, Pax8 lineage recombination in these mice occurs in tubular epithelium, but not in vasculature, providing a model of cystic kidney disease in which Pkd1 is not deleted from ECs." (PMID 40114603, 2025). "Unlike in the mouse model, this PKD1 KO pig model displayed renal cyst formation at a young age." (PMID 34980882, 2022). "Interestingly, PKD1 heterozygote mice do not present with renal cysts, however, the deletion of this Ca2+ channel in PKD1 heterozygotes can result in the formation of extremely large renal cysts in a few of the cases." (PMID 34828368, 2021). "Treatment with cystic cell-derived EVs/exosomes decreased Pkd1 mRNA and proteins in recipient cells and in cystic kidneys, suggesting that EVs/exosomes may be a nongenetic factor that lowers the amount of polycystin 1 in the cystic kidneys." (PMID 34315885, 2021).
Renal cyst (continued). "However, the fact that several cysts in ADPKD tissue and Pkd1 mutant kidneys appear to be negative to upregulation of mTORC1 calls into question the essential role of this cascade in the formation of renal cysts." (PMID 19863783, 2009). "However, among patients with no family history (the 10–25% who have no parent with ADPKD), some 40% reportedly have no observed mutation in the PKD1 or PKD2 genes; this suggests that careful diagnosis is required to differentiate between ADPKD and other cystic kidney diseases." (PMID 36362756, 2022). "We observed that inactivation of the Pkd1 gene generated a truncated tagged protein lacking the C-terminal domain and resulting in a phenotype very similar to the one described for all other knock-out lines, including oedema, haemorrhage, and cystic kidneys by day E15.5." (PMID 19774080, 2009). "Insights from an animal model featuring altered loci for both PKD1 and ATM (Pkd1RC/RC/Atm+/− or Pkd1RC/RC/Atm−/−) revealed no discernible alteration in the progression of cystic kidney disease, even at the age of 6 months." (PMID 38474184, 2024). "To further investigate the metabolic changes induced by both Pkd1 gene disruption and a long salsalate treatment, we performed NMR metabolomic analysis to quantitatively measure metabolite levels within cystic kidneys with and without long salsalate treatment." (PMID 38026227, 2023). "Our experimental data show that applications of a DA1 antagonist at the precystic stage prevented renal cyst formation only in Pkd2–/–, which had impaired GTB, but not in Pkd1–/–, which had intact GTB." (PMID 33886508, 2021). "The Pkd1flox/flox:Nestincre mice present cystic kidneys, reproducing the ADPKD phenotype, however do not have a systemic Pkd1-haploinsufficiency background." (PMID 31937827, 2020). "Alternatively, FGF23 mRNA and protein expression was detected in cell lining renal cysts, but not in bone of the cy/+ Han:SPRD rat model of PKD; similar finding was also observed in an inducible Pkd1 knockout mouse model, suggesting ectopic expression of FGF23 in CKD." (PMID 25464512, 2014).
end-stage renal disease (43 papers, 2006 to 2025). "PKD2 mutations tend to manifest in older individuals, presenting with milder symptoms, fewer kidney cysts, delayed hypertension onset, and less frequent end-stage renal disease than PKD1 mutations." (PMID 38989164, 2024). "Mutations within PKD1 gene are reportedly associated with earlier onset of end-stage renal disease when compared to those with PKD2 mutations." (PMID 35629189, 2022). "PKD2 mutation causes end-stage renal disease at an average age of 74 years, which occurs in 10–15% of cases; on the other hand, PKD1 mutation results in end-stage renal disease at an average age of 54 years which occurs in 80–90% of total cases of ADPKD." (PMID 32957937, 2020). "The mutational analysis of the PKD1 gene in the patient with advanced chronic renal insufficiency was therefore employed in attempt to identify the causative mutation." (PMID 23496908, 2013). "Patients with PKD2 mutation have a later onset of disease and develop end-stage renal failure later than those with PKD1 mutation." (PMID 23304619, 2012). "Three newly described framesfift mutations in PKD1 seem to be associated with more severe clinical course of the disease resulting in ESRD (End Stage Renal Disease) in the age range of 44 to 48 years." (PMID 16430766, 2006). "To determine whether this pathway has translational relevance, we examined tissue from 3 normal human kidneys, a patient with a known PKD2 mutation, and 3 patients who likely have a PKD1 mutation based on the age of onset of end-stage renal disease (ESRD)." (PMID 40763312, 2025). "This study aims to investigate the serum proteomic of cats with PKD1 heterozygous gene mutation and compare it with chronic kidney disease cats and Normal wild‐type cats using MALDI‐TOF MS (Matrix‐Assisted Laser Desorption/Ionization Time‐of‐Flight Mass Spectrometer)." (PMID 38053473, 2023). "The proband, with an extremely serious manifestation of ADPKD (the man was diagnosed in early childhood, and with end stage renal disease aged 23), underwent genetic analysis of PKD1 and PKD2, which revealed the presence of pathogenic mutations in both of these genes." (PMID 29973168, 2018). "Observational studies have shown that age, male sex, hypertension, truncating PKD1 mutations, and TKV are associated with an increased risk of chronic kidney disease (CKD) progression." (PMID 36342644, 2023). "The renal survival rate of ADPKD patients with PKD1 mutations (77/112) was significantly lower than that of those with PKD2 mutations (9/16), leading to an earlier onset of end-stage renal disease (ESRD)." (PMID 36186434, 2022). "The two causative genes are PKD1 and PKD2, and end-stage renal disease (ESRD) tends to occur around 53 years of age in patients with PKD1 and 68 years of age in patients with PKD2, respectively." (PMID 32178226, 2020). "Mutations in PKD1 and PKD2 have a similar clinical phenotype characterized by the slow development of multiple fluid-filled kidney cysts, leading to end stage renal failure at an average age of 54yrs in PKD1 and 74yrs in PKD24." (PMID 32001768, 2020). "A grandmother with the PKD1 gene mutation in mosaicism (p.Val1105ArgfsX4) and with mild clinical course of ADPKD (end stage renal failure at the age of 77) seemed to have ADPKD because of PKD2 gene mutation." (PMID 23496908, 2013). "The average age of PKD1 patients at end-stage renal disease (ESRD) is 54.3 years compared with 74.0 years for PKD2 patients." (PMID 19686598, 2009). "Three newly described framesfift mutations in PKD1 c.12772dup, c.11820_11845del and c.11693_11697dup seem to be associated with the more severe clinical course of the disease resulting in ESRD (End Stage Renal Disease) in the range from 44 to 48 years." (PMID 16430766, 2006). "Additionally, 50% of the studied PKD1/PKD2 affected individuals reached a high disease grade (G4/5) or end-stage renal disease (ESRD)." (PMID 36422197, 2022).
end-stage renal disease (continued). "Mutation either in the PKD1 (approximately 85% of patients) or PKD2 gene (approximately 15%) cause ADPKD, with an average age of 54.3 and 74 years, respectively, at the onset of ESRD (end stage renal disease)." (PMID 23496908, 2013). "Genotype-phenotype correlations showed that patients with PKD1 variants predicted to truncate (T) the protein experienced end-stage renal disease 9 years earlier than patients with PKD1 non-truncating (NT) mutations and >13 years earlier than patients with PKD2 mutations." (PMID 32457805, 2020). "Furthermore, patients with PKD1-truncating mutations reached end-stage renal disease (ESRD) earlier than patients with non-truncating mutations (47 ± 3.522 years vs. 59 ± 11.687 years, P = 0.016)." (PMID 26632257, 2015). "The presence of TSC2 and PKD1 gene deletions should be considered in the clinical assessment of TSC in children with early-onset PKD and in all patients with ADPKD who develop end-stage renal failure prior to the fourth or fifth decade of life." (PMID 31870441, 2019). "Several reports characterized TSC2/PKD1 CGS as a severe polycystic kidney growth with onset and end-stage renal failure at an early age." (PMID 31870441, 2019). "We conducted a longitudinal retrospective cohort study to assess the association between sex of the affected parent and time to hypertension diagnosis, end-stage renal disease (ESRD), and death in patients with the PKD1 genotype." (PMID 29035198, 2018). "Obviously, the genetic diagnosis of TSC2/PKD1-CGS predicts the appearance of a more severe phenotype, and affected patients need improved attention with assistance to prepare for earlier occurring end-stage renal disease." (PMID 36979978, 2023).
Hypertension (42 papers, 2013 to 2025). The presence of chronic increased pressure in the systemic arterial system. "The prevalence of arterial hypertension is comparable to that observed in patients with pathogenic variants in PKD1/2." (PMID 40428294, 2025). "The first is an association between PKD1 and hypertension, which can be detected at larger sample sizes." (PMID 41136342, 2025). "Compared with the SPs, there were higher proportions of patients who had hypertension before 35 years of age, first urologic event of macroscopic hematuria, cyst infection before 35 years of age, PKD1 PT mutation, and PKD1 NT mutation in the RPs." (PMID 37705904, 2023). "Research published focusing on patients who are positive for polycystic kidney disease 1 (PKD1) mutations prior to the age of 35 years show a worse and faster disease progression in the male sub-cohort and/or hypertension." (PMID 31590248, 2019). "The canonical PKD1 activation pathway has been implicated in the pathological remodeling events in the heart that occur in response to hypertension." (PMID 29930945, 2018). "The presence of hypertension along with at least one urologic complication, or the presence of a truncating PKD1 mutation was reported to be associated with poorest renal outcome." (PMID 26275819, 2015). "The factors related to greater ADPKD severity are primarily carrying a PKD1 mutation, especially if truncating, and hypertension." (PMID 24007508, 2013). "Association between LVH and PKD1 mutation adjusted for hypertension, age, gender and anaemia." (PMID 41195291, 2025). "Notably, children classified in higher LIC risk categories had an increased incidence of hypertension and a higher prevalence of PKD1 mutations." (PMID 38464892, 2024). "We believe ascertainment bias of patients with PKD1 variants in the 100KGP might explain this, as patients with PKD1 variants tend to present earlier to healthcare services with hypertension and other sequelae." (PMID 39190485, 2024). "Additionally, PKD1 mutation carriers generally have a poorer renal prognosis and develop hypertension earlier than PKD2 mutation carriers." (PMID 39457385, 2024). "Thus, the PKD1 gene was linked to both essential hypertension and secondary hypertension." (PMID 37059828, 2023). "Only the individual with the TSC2/PKD1 deletion was diagnosed with hypertension and decreased kidney function." (PMID 37386496, 2023). "The finding that the gene collapsing analyses in essential hypertension identified variation in genes (PKD1, PKD2, COL4A4, UMOD, CACNA1D, and NR3C2) that are possible causes of undiagnosed secondary hypertension is worthy a special comment." (PMID 37059828, 2023). "Generally, pathogenic variants in PKD1 are phenotypically severe with higher incidence of ESRD and arterial hypertension." (PMID 32779812, 2020). "Subjects with the PKD1-PT genotype had an early onset of hypertension, larger htTKV, lower eGFR, and more frequent ESRD incidence than other genotypes." (PMID 31740684, 2019). "A key substrate of PKD1 in hypertension-induced cardiac remodeling is histone deacetylase-5 (HDAC5), a member of the HDAC family negatively regulating the acetylation status of nucleosomal histones, and thereby repressing transcription." (PMID 29930945, 2018). "The USRDS also does not have information on ADPKD genotype, and we thus cannot distinguish between genotype PKD1 vs. genotype PKD2, which generally has a more indolent course than PKD1, ie later age at diagnosis, and later onset of hypertension and ESRD." (PMID 24571546, 2014). "We demonstrate, for the first time to our knowledge, a strong association between LVH and the presence of PKD1 mutations, an effect independent of traditional risk factors like hypertension." (PMID 41195291, 2025). "Mitral valve prolapse was associated with truncating PKD1 mutations (P = .007), independent of hypertension, age, sex and anaemia (adjusted OR 3.950, P = .037)." (PMID 41195291, 2025).